RNU6-126P (RNA, U6 small nuclear 126, pseudogene)
Gene: Small nuclear RNA gene on chromosome 11 (78,133,420 to 78,133,522, reverse strand). Ensembl gene ENSG00000252494.
Homologues: Orthologues: chimpanzee U6 (99% identical), macaque U6 (95% identical), dog U6 (65% identical), guinea pig U6 (63% identical), guinea pig U6 (60% identical), rabbit U6 (59% identical), guinea pig U6 (57% identical), mouse Gm26403 (50% identical). Paralogues in human: RNU6-181P (73% identical), RNU6-1323P (72% identical), RNU6-234P (72% identical), RNU6-400P (72% identical), RNU6-580P (72% identical), RNU6-831P (72% identical), RNU6-836P (72% identical), RNU6-878P (72% identical), RNU6-1145P (71% identical), RNU6-1283P (71% identical), RNU6-188P (71% identical), RNU6-196P (71% identical), and 1283 more.